TKT (transketolase)
Diseases named in the same sentence as TKT in open-access papers (continued):
Sharing a sentence is not in itself a finding about the gene and the disease.
tumor (continued). "ScRNA-Seq data showed that TKT expression was relatively high in mono/macro, with fluctuations at specific differentiation stages, suggesting a potential role in macrophage polarization and adaptation within the tumor microenvironment." (PMID 40230848, 2025). "Many studies have shown that the activity of TKT in tumors may be related to tumor growth and metabolic regulation." (PMID 40227333, 2025). "TKT, as a potential therapeutic target, may provide new treatment strategies and methods by inhibiting the activity, affecting the growth of tumor cells and metabolic pathways." (PMID 40227333, 2025). "Single-cell transcriptomics identified a tumor cell subpopulation (NB3) and two tumor-associated macrophage (TAM) subpopulations (SPP1+ TAMs and IGHM+ TAMs) closely associated with BBM and highlighted transketolase (TKT) as a key molecular marker for metastatic progression in NB." (PMID 40070366, 2025). "Overall, these findings highlight TKT as a potential modulator of multiple oncogenic pathways that may contribute to tumor growth and metastasis in HCC." (PMID 40230848, 2025). "Although there are currently no studies directly exploring the relationship between TKT and TMB, its biological role indicates that high TKT expression could indirectly contribute to elevated TMB by increasing genomic instability in tumor cells." (PMID 40230848, 2025). "The increased expression of TKT in these regions may reflect its role in promoting immune evasion, tumor cell survival, and adaptation within the complex tumor microenvironment." (PMID 40230848, 2025). "We detect TKT protein expression in tumor and adjacent tissues performed by immunohistochemistry." (PMID 38434975, 2024). "We speculate that TKT promotes the process of glycolysis and maintains the acidic tumor microenvironment, which facilitates metastasis of GC cells." (PMID 37817120, 2023). "Accordance with our previous reports that PDH was restrained by 150 mg/kg OT in mice, we therefore assume that OT may promote apoptosis via adjust the expression of PDH/PDK or TKT in tumor cells." (PMID 35603057, 2022). "Studies revealed that TKT knockdown caused R5P accumulation by affecting the provision of NADPH to counteract ROS, as well as promoting genome instability during liver injury and tumour initiation." (PMID 36314067, 2022). "In contrast, inhibition of TKT reduces tumor malignancy in CRC." (PMID 35280908, 2022). "Furthermore, the in vivo study revealed that knockdown of NRF2 markedly decreased the protein levels and enzymatic activities of G6PD and TKT in the excised tumors from Ca9-22-D1 xenograft tumor-bearing mice." (PMID 33859744, 2021). "Furthermore, OT itself has an anti-proliferative effect on tumor cells at a relatively high concentration (10 mM) in vitro and in vivo, in part due to the inhibition of the transketolase (a key enzyme in the pentose-phosphate pathway)." (PMID 34503102, 2021). "Here, the sustained activation of NRF2 due to KEAP1 LOF mutation was seen to promote tumor growth and upregulate the expression of PPP genes, including G6PD, TKT and PGD, through the epigenetic inhibition of miR-1 and miR-206, two repressors of metabolic gene induction." (PMID 32443774, 2020). "In vitro experiments showed that the NLS mutations decreased the pro-tumor function of TKT independent of its enzymatic activity, implying non-metabolic functions of TKT in the HCC nucleus." (PMID 30971297, 2019). "We further identified the nuclear localization sequences (NLS) for TKT and demonstrated the NLS mutations decreased the pro-tumor function of TKT independent of the enzyme activity." (PMID 30971297, 2019). "We found high TKT expression was significantly correlated with characteristics of a poor prognosis, such as a high TNM stage (P = 0.013), microvascular invasion (P < 0.001) and loss of tumor encapsulation (P = 0.028)." (PMID 30971297, 2019). "The results showed that TKT expression was positively correlated with subcutaneous tumor size." (PMID 30971297, 2019).
tumor (continued). "Of these, up-regulation of TKT occurs in cancerous tissue and promotes tumor progression." (PMID 30459934, 2018). "TKT links glycolysis with the pentose phosphate pathway (PPP) by catalyzing a reversible reaction that produces ribose-5-phosphate for use in nucleotide synthesis essential to tumor cell proliferation." (PMID 30459934, 2018). "TKT activity has been reported to have a high control coefficient of tumor growth in mice with Ehrlich’s ascites tumor and to be increased in (pre)neoplasic lesions in rat liver and pancreatic adenocarcinoma, where the nonox-PPP is the main pathway responsible for riboneogenesis." (PMID 29290982, 2017). "Altogether, both G6PD and TKT are crucial enzymes in modulating the tumor metabolic phenotype." (PMID 29290982, 2017). "A decrease in Transketolase expression levels in tumor cells was assumed to delay tumor growth." (PMID 26861291, 2016). "Our findings suggest that TKT may play a role in tumor immunity and prognosis in HCC." (PMID 40230848, 2025). "Thus, TKT may be a new biomarker, and its inhibition could be a promising strategy for tumor treatment." (PMID 40230848, 2025). "Moreover, the involvement of oxidative phosphorylation and ribosomal activity indicates that TKT may enhance the metabolic capacity of tumor cells, enhancing energy production and protein synthesis needed for tumor growth." (PMID 40230848, 2025). "Besides, TKT inhibitor promotes tumor cell apoptosis and cell cycle blockade." (PMID 35711845, 2022). "No transketolase activity of TKTΔ38 can be detected for conversion of physiological sugar substrates thus arguing against an intrinsically encoded enzymatic function of TKTL1 in tumor cell metabolism." (PMID 23118983, 2012). "Moreover, when TKT is activated by addition of its cofactor, thiamine, tumor growth is stimulated." (PMID 21980427, 2011). "Therefore, transketolase upregulation in tumor progression seems very likely." (PMID 19545368, 2009). "In this study, we demonstrate that TKT promotes glucose metabolism in RCC by enhancing glycolysis, thereby supporting tumor progression." (PMID 41253799, 2025). "According to our existing experimental results, chaetocin can inhibit the enzyme activity and expression of TKT, and then inhibit NADPH, resulting in the surge of ROS and leading to apoptosis of drug-resistant tumor cells." (PMID 40227333, 2025). "These clinical correlations align with functional studies showing that TKT enhances RCC cell migration, invasion, and proliferation in vitro, as well as metastatic dissemination and tumor growth in vivo." (PMID 41253799, 2025). "In this study, we provide compelling evidence that TKT expression is significantly elevated in RCC tissues and correlates with adverse clinical outcomes, including larger tumor size, advanced TNM stage, and reduced overall survival." (PMID 41253799, 2025). "Transketolase (TKT) and transaldolase (TAL) are the key enzymes involved in radical metastasis, and are closely related to tumor growth." (PMID 39330497, 2024). "Therapeutics targeting TKT with an inhibitor, oxythiamine, reduced HMGA1-induced ESCC cell proliferation and tumor growth." (PMID 39080260, 2024). "By targeting TKT, oroxylin A inhibits the non‐oxidative PPP and HCC tumour growth in mice and patient‐derived organoids (PDOs)." (PMID 36314067, 2022). "The expression of differential genes related to PPP, including TKT, TKTL1, PGM1, GPI, FBP2, ALDOA and ALDOC, were all upregulated in WDLPS tumor samples, which were validated by Real-time Quantitative PCR (RT-qPCR)." (PMID 36557266, 2022). "Some studies have pointed out that high expression of TKT in cervical cancer and pancreatic cancer enhance the PPP activity, thereby providing raw materials for the rapid growth and proliferation of tumor cells." (PMID 35110545, 2022).
tumor (continued). "In support of the SIRT5–TKT axis, TKT overexpression rescued SIRT5 silencing-induced decreased tumor volume and weight, downregulation of R5P and nucleotide levels, as well as DNA damage and cell apoptosis." (PMID 36253417, 2022). "To investigate the possible mechanism of TKT in CRC metastasis, we determined the possible genes from the previous mass spectrometry results and focused on GRP78 because GRP78 promotes tumor growth and migration via regulating AKT phosphorylation." (PMID 35110545, 2022). "Previous reports showed that TKT inhibition decreased PPP flux and increased sensitivity to gemcitabine and imatinib in tumour cells." (PMID 35752610, 2022). "Our findings suggested that oroxylin A was a potent TKT inhibitor, and also inhibited non‐oxidative PPP and HCC tumour growth in mice and PDOs for the first time." (PMID 36314067, 2022). "The direct relationship between the activity of transketolase in the peritumoral zone of the tumor and IDH1 was found with the local clustering coefficient between IDH1 and transketolase −0.637." (PMID 35625744, 2022). "Accordingly, the stable knockdown of KEAP1 was also found to enhance while NRF2 silencing repressed the expression of TKT in HCC cells, wherein this enzyme promoted NADPH synthesis, tumor growth, metastasis formation and sorafenib resistance." (PMID 32443774, 2020). "Accordingly, the use of TKT inhibitor oxythiamine (OT) significantly sensitized human HCC cells to sorafenib treatment in vitro and suppressed tumor growth in vivo." (PMID 28553614, 2017). "Strikingly, and counterintuitively to the anti-tumor activity of DIO1, restoration of DIO1 expression resulted in moderate increase of TKT, NAMPT and IDH2 protein levels." (PMID 29272308, 2017). "TKT and G6PD have been postulated as relevant enzymes in tumor cells by different studies, but little is known about the impact of the expression level of these enzymes on disease progression and survival." (PMID 29290982, 2017). "Costunolide-mediated decrease in tumor volume was accompanied by decreased expression of TERT, Nrf2, G6PD, TKT, and GS(P) levels." (PMID 27148686, 2016). "Transketolase (TKT) or transketolase-like protein 1 (TKTL1), enzymes in the PPP, sustains viability of tumor cells and confers resistance to anti-EGFR antibody therapy and imatinib." (PMID 25693144, 2015). "Therefore, metabolic interventions targeting PPP, particularly TKT/TKTL1, represent a promising immunotherapeutic strategy to enhance macrophage anti-tumor functions and improve cancer immunotherapy outcomes." (PMID 40076729, 2025). "Moreover, the cooperative regulation of RCC metabolism by TKT and PKM2 highlights a potential metabolic vulnerability in tumor cells." (PMID 41253799, 2025). "According to the IHC score, the expression of TKT in tumor was higher than that in non-tumor tissues." (PMID 38434975, 2024). "Particularly, TKT holds a key position, since it connects PPP with glycolysis, affecting the production of the antioxidant NADPH, and its blockade has been reported to increase oxidative stress, making tumor cells more vulnerable to therapeutic treatment." (PMID 38132097, 2023). "Remarkably, our study showed that the inhibition of the enzyme activity of TKT did not entirely abolish the tumor-promoting effects in HCC cells." (PMID 30971297, 2019). "In this case, despite of transketolase inhibition, there was no apparent effect on tumor cell growth." (PMID 29208764, 2018). "While overexpression of mutated TKTL1 has been reported in urothelial and colorectal cancer and correlated with tumor invasiveness as well as predicted poor patient outcome, TKT and TKTL2 expression were not altered in this study." (PMID 28553614, 2017). "TKT expression was positively associated with aggressive clinicopathological HCC features (presence of venous invasion, increased tumor size, absence of tumor encapsulation)." (PMID 28553614, 2017).
tumor (continued). "Transketolase reactions in the pentose phosphate pathway (PPP) convert glucose to ribose for nucleic acid synthesis and generate NADPH, a reducing agent required for synthesis reactions in growing tumour cells." (PMID 21854597, 2011). "The non-oxidative arm of PPP seems to be moreimportant for tumor cells based on higher expression and activity of transketolase(TKTL1) found to correlate with rate of tumor growth in some cancers including GBMs." (PMID 21317451, 2010). "Here, we provide evidence that TKTL1 mRNA and protein are specifically overexpressed in tumours, whereas TKT and TKTL2 expression are not upregulated." (PMID 16465194, 2006). "TKT is a thiamine diphosphate-dependent enzyme and elevated TKT activity may enhance the PPP and promote synthesis of 5-phosphoribose and NADPH, leading to nucleotide synthesis, inhibition of oxidative stress, and rapid proliferation of tumor cells." (PMID 38434975, 2024). "Except for TKT gene, all PPP-related genes are not differentially expressed, whereas the expression of genes encoding enzymes of upper and lower glycolysis is largely affected between tumour subtypes, also compared to the healthy counterparts." (PMID 37198319, 2023). "TKT is one of the metabolic enzymes in the nonoxidative phase of the pentose phosphate pathway, which plays an important role in promoting the rapid proliferation of tumor cells." (PMID 31949131, 2020). "There is experimental evidence that TKT activity can be effectively inhibited by applying coenzymatically inactive thiamin analogs, which in some but not all instances reduced the proliferation of tumor cells." (PMID 23118983, 2012). "The expression of TKT protein in HCC and tumor adjacent non-cancerous tissues was detected by immunohistochemistry." (PMID 38434975, 2024). "The enzymatic properties of TKTL1, its upregulation in tumours, and the absence of upregulation of TKT and TKTL2 indicate that TKTL1 is the transketolase targeted by anti-transketolase drugs." (PMID 16465194, 2006). "So far, three human transketolase genes have been recognised, and the relative contributions of TKT, transketolase-like-1 (TKTL1), and transketolase-like-2 (TKTL2) to tumour-specific transketolase metabolism have not been investigated." (PMID 16465194, 2006). "TKT, as a key enzyme in the non-oxidative PPP, supplies more R5P to facilitate tumor proliferation." (PMID 36253417, 2022). "Transketolase (TKT) is one of the key enzymes in the nonoxidative part of the pentose phosphate pathway (PPP), and PPP provides approximately 85% of the pentose sugar required for DNA synthesis in tumor cells." (PMID 33520706, 2020). "TKT, a critical metabolic enzyme in the non-oxidative branch of PPP, catalyzes reactions that enable oxygen-independent glucose degradation and that play a crucial role in the biosynthesis of ribose-5-phosphate in tumor cells." (PMID 24666435, 2014). "Transketolase enzyme reactions of the nonoxidative part of the PPP enable oxygen-independent glucose degradation, and play a crucial role in nucleic acid ribose synthesis utilising glucose carbons in tumour cells." (PMID 16465194, 2006). "Herein our data indicated that SIRT5 silencing increased the lysine malonylation levels of TKT, thereby suppressing the non-oxidative PPP and leading to insufficient R5P levels for nucleotide synthesis, which contributed to DNA damage and growth inhibition of tumor cells." (PMID 36253417, 2022).
infection (25 papers, 2010 to 2025). The state of being infected such as from the introduction of a foreign agent such as serum, vaccine, antigenic substance or organism. "We conclude that M. oryzae metabolism is dedicated to metabolizing glucose through transketolase in planta in order to provide ATP as a trigger for biotrophic growth and infection." (PMID 25188286, 2014). "Whether an expressed transketolase ortholog of TKL1 in P. palmivora (PLTG_04838) is also involved in early infection processes remains to be addressed." (PMID 31575765, 2019). "The data show that TKT is essential to L. mexicana in establishing mammalian infection." (PMID 29554142, 2018). "Among the metabolic genes, Transketolase (TKT) and Succinate dehydrogenase subunit A (SDHA) were down-regulated by either KSHV-infection or CoCl2 treatment." (PMID 29746587, 2018). "The two enzymes of the non-oxidative PPP, transketolase and transaldolase, have minor regulation but are expressed throughout infection." (PMID 32255806, 2020). "In the non-oxidative PPP T. gondii transketolase is expressed at 20 to 40 FPKM from 6 to 48 HPI while transaldolase is highly expressed throughout infection with FPKM values over 100 from 6 to 36 HPI." (PMID 32255806, 2020). "Although initial infection was equal in all groups, significant increase was observed in WT (9.3 fold, p = 2.9 x 10−4) and Δtkt + TKT (5.5 fold, p = 0.0057) after 96 h, but no significant increase was observed in Δtkt." (PMID 29554142, 2018). "Most intriguingly, TKT knockout cells were not able to establish infection in mice, although cells re-expressing the enzyme were, indicating the TKT is essential to Leishmania and a possible target for chemotherapy." (PMID 29554142, 2018). "Overall, knockdown of 21 (95% of 22) TRP32 target proteins significantly reduced ehrlichial infection, while knockdown of only 1 (5%) protein (transketolase [TKT]) did not have significant impact on infection." (PMID 28553621, 2017).
neurological disorders (6 papers, 2020 to 2025). "Among these various interacting genes, four (RAF1, BRD4, ATRX, and TKT) have been associated with syndromic congenital conditions involving craniofacial abnormalities, heart defects, and neurological disorders." (PMID 40525707, 2025). "In module-5, VCP shown interaction with 5 proteins (AKTI, CAV1, HSPA8, DNM1L, TKT) functionally associated with enzyme binding processes and most of these genes are mostly related to neoplasms disorder followed by nervous system diseases." (PMID 34918006, 2022).
neurodegenerative disease (3 papers, 2024). A disorder of the central nervous system characterized by gradual and progressive loss of neural tissue and neurologic function. "Here, we characterize the brain TKT regulation by acylation in rats with perturbed thiamine-dependent metabolism, known to occur in neurodegenerative diseases." (PMID 38255994, 2024).
cardiovascular disease (2 papers, 2021 to 2022). "The potential activation of transketolase through benfotiamine contributes to the inhibition of 3 out of 4 mechanisms that damage blood vessels, reducing the risk of cardiovascular disease (CVD)." (PMID 33652684, 2021). "Six genes (TKT, TCF4, SWAP70, DDHD2, ARHGAP31, and LTB) showed significant associations of genetic variants with the risk of cardiovascular disease." (PMID 36204511, 2022).
infectious disease (2 papers, 2017 to 2019). A disorder directly resulting from the presence and activity of a microbial, viral, or parasitic agent in humans. "In addition, TKT seems to be a better biomarker than CD93 for reflecting renal involvement because the level of TKT was less elevated than that of CD93 in patients with infectious diseases." (PMID 28962592, 2017). "In contrast, the serum levels of TIMP1, TKT, and CD93 were significantly higher in patients with active AAV than in those with infectious diseases." (PMID 28962592, 2017).
metabolic disease (2 papers, 2020 to 2021). A congenital disorder (due to inherited enzyme abnormality) or acquired (due to failure of a metabolically important organ) disorder resulting from an abnormal metabolic process. "Hence, PPP enzymes such as G6PD, including 6PGD and TKT, are promising targets for the treatment and anticipation of metabolic diseases." (PMID 34827081, 2021).
intestinal disorder (1 paper, 2021). A non-neoplastic or neoplastic disorder that affects the small or large intestine. "Therefore, our data demonstrate that TKT serves as an essential guardian of intestinal integrity and barrier function as well as a potential therapeutic target for intestinal disorders." (PMID 34535624, 2021).